ENSG00000239182
Synonyms: LOC124900501
Gene: Small nucleolar RNA gene on chromosome X (118,738,055 to 118,738,182, forward strand). Ensembl gene ENSG00000239182.
Gene Ontology:
Biological process: RNA processing
Cellular component: nucleolus
Homologues: Paralogues in human: SNORA35B (60% identical), SNORA35 (54% identical).